ENSG00000254706 (novel protein)
Gene: Protein-coding gene on chromosome 1 (162,365,407 to 162,383,531, forward strand). Ensembl gene ENSG00000254706.
Genetic constraint (gnomAD): Loss-of-function variants: 4 observed, 11.13 expected, observed/expected ratio (o/e) 0.36, 90% interval 0.18 to 0.82. Missense variants: 183 observed, 204.09 expected, observed/expected ratio (o/e) 0.9, 90% interval 0.79 to 1.01. Synonymous variants: 80 observed, 86.63 expected, observed/expected ratio (o/e) 0.92, 90% interval 0.77 to 1.11.